C12orf57 (chromosome 12 open reading frame 57)
Description:
In brain, may be required for corpus callosum development.
Synonyms: C10; GRCC10
Tractability: PROTAC: ubiquitination databases record sites on it.
Gene: Protein-coding gene on chromosome 12 (6,942,938 to 6,946,003, forward strand). Ensembl gene ENSG00000111678.
Subcellular location: Cytoplasm
Subcellular location (Human Protein Atlas): Nuclear speckles
Gene Ontology:
Molecular function: protein binding
Biological process: camera-type eye morphogenesis; cognition; corpus callosum morphogenesis; post-embryonic development; psychomotor behavior; regulation of skeletal muscle contraction; third ventricle development
Cellular component: cytoplasm; nuclear speck
Genetic constraint (gnomAD): Loss-of-function variants: 14 observed, 12.27 expected, observed/expected ratio (o/e) 1.14, 90% interval 0.75 to 1.73. The upper end of that interval is the gene's LOEUF score, 1.73, which puts it in group 6 of 6, group 1 being the genes least tolerant of losing a copy. Missense variants: 229 observed, 182.55 expected, observed/expected ratio (o/e) 1.25, 90% interval 1.12 to 1.4. Synonymous variants: 100 observed, 81.17 expected, observed/expected ratio (o/e) 1.23, 90% interval 1.05 to 1.46.
Homologues: Orthologues: macaque C11H12orf57 (98% identical), mouse Grcc10 (98% identical), pig C12orf57 (98% identical), rabbit C12orf57 (97% identical), guinea pig C12orf57 (96% identical), dog C12orf57 (74% identical), zebrafish C20H12orf57 (70% identical), tropical clawed frog c7h12orf57 (56% identical), Drosophila melanogaster CG15387 (29% identical).
Diseases named in the same sentence as C12orf57 in open-access papers:
C12orf57 is named in the same sentence as 27 diseases in open-access papers, as found by Europe PMC text mining. Sharing a sentence is not in itself a finding about the gene and the disease. The quoted sentences say what the papers report.
temtamy syndrome (4 papers, 2017 to 2025). Temtamy syndrome is a very rare congenital genetic neurological disorder characterized by agenesis/hypoplasia of corpus callosum with developmental abnormalities, ocular disorders, and variable craniofacial and skeletal abnormalities. "Besides, C12orf57 is associated with Temtamy syndrome comprised of hypotonia, moderate to severe ID with ASD features, corpus callosum hypoplasia, seizures, and microphthalmia." (PMID 38572415, 2024).
microphthalmia (2 papers, 2014 to 2024). Congenital or developmental anomaly in which the eyeballs are abnormally small. "Mutations in C12orf57 have recently been identified in patients with colobomatous microphthalmia associated with developmental delay, seizures and corpus callosum abnormalities suggesting a role at similarly early levels of development." (PMID 24412933, 2014).
nephrotic syndrome (1 paper, 2025). A collection of symptoms that include severe edema, proteinuria, and hypoalbuminemia; it is indicative of renal dysfunction. "Our study further detected pathogenic variants in genes (C12orf57) and regions (Chr16.11P2) that were not previously linked to kidney diseases, which may play a role in the nephrotic syndrome phenotype if other similar families are reported in the future." (PMID 40402239, 2025).
C12orf57 also shares sentences with these, for which no sentence is quoted: tumor (5 papers); infection (4); cancer (3); kidney diseases (2); Arrhythmogenic right ventricular dysplasia (1); Birk-Barel syndrome (1); brain disease (1); brain tumors (1); Chediak-Higashi syndrome (1); Cohen syndrome (1); deafness (1); developmental delay (1); dystroglycanopathies (1); Escobar syndrome (1); glioma (1); glomerular disease (1); keratoconus (1); malignant brain tumors (1); muscular dystrophy (1); Nephropathy (1); neurological disorders (1); Opportunistic infection (1); Rubinstein-Taybi syndrome 1 (1); ZIKV infection (1).